KIR2DL1 (killer cell immunoglobulin like receptor, two Ig domains and long cytoplasmic tail 1)
Diseases named in the same sentence as KIR2DL1 in open-access papers (continued):
Sharing a sentence is not in itself a finding about the gene and the disease.
infection (10 papers, 2014 to 2023). The state of being infected such as from the introduction of a foreign agent such as serum, vaccine, antigenic substance or organism. "This unhealthy oral environment is more prone to infection and colonization with Fn, which induces high expression of KIR2DL1 on the surface of CD8+ T cells." (PMID 34935568, 2022). "Cohen's kappa coefficients indicate the consistency between Fn infection and expression of the inhibitory receptor KIR2DL1 on the surface of CD8+ T lymphocytes in ESCC [n (%)]." (PMID 34935568, 2022). "However, since KIR2DL1/HLA-C*04 interaction was associated with a higher rate of relapse, immunosuppression caused by intensification treatments could be the main reason for infection and death." (PMID 34064810, 2021). "This was of interest as HCMV downregulates HLA class I molecules, and a decrease in KIR2DL1 reporter activation over infection time was expected." (PMID 28424684, 2017). "Authors described that the main cause of death associated with SHS was an infection, which poses a new question for our study: could the KIR2DL1/HLA-C*04 interaction be related to defective protection against infections instead of to an altered antitumor response?" (PMID 34064810, 2021).
hematologic malignancies (2 papers, 2023 to 2025). "Lirulimab, a mAb that blocks KIR2DL1 and KIR2DL2/L3, has been developed as an NK therapeutic and tested in human clinical trials to treat solid tumors and hematologic malignancies; it could potentially be repositioned to alter T cell lifespan." (PMID 37071474, 2023).
KIR2DL1 also shares sentences with these, for which no sentence is quoted: melanoma (4 papers); breast carcinoma (3); liver cancer (2); vitiligo (2); Ascites (1); autoimmune disease (1); Behcet syndrome (1); bladder carcinoma (1); co-infection (1); colorectal tumors (1); diabetic nephropathy (1); end-stage renal disease (1); esophageal squamous cell carcinoma (1); fibrosis (1); Hypertension (1); immune dysfunction (1); LGL leukemia (1); lymphoma (1); lymphopenia (1); lymphoproliferative disorders (1); nephritis (1); neuroblastoma (1); NK cell leukemia (1); non-small cell lung carcinoma (1); Obesity (1); ocular toxoplasmosis (1); of pregnancy (1); ovarian carcinoma (1); psoriasis (1); rheumatoid arthritis (1).
A further 2 diseases each share a sentence with KIR2DL1 in 1 paper.